KCNJ2 (potassium inwardly rectifying channel subfamily J member 2)
Diseases named in the same sentence as KCNJ2 in open-access papers (continued):
Sharing a sentence is not in itself a finding about the gene and the disease.
Arrhythmia (43 papers, 2004 to 2026). Any cardiac rhythm other than the normal sinus rhythm. "The Anderson-Tawil syndrome (ATS), characterized by periodic paralysis, cardiac arrhythmias, and dysmorphic features, is caused by loss-of-function mutations in the KCNJ2 gene." (PMID 38683369, 2024). "Short QT syndrome type 3 (SQTS3 or SQT3), which is associated with life-threatening cardiac arrhythmias, is caused by heterozygous gain-of-function mutations in the KCNJ2 gene." (PMID 39769116, 2024). "Following the association of the KCNJ2 mutations with cardiac arrhythmia symptoms, ATS type-1 was diagnosed in the carriers of both mutations." (PMID 32499698, 2020). "Two genes associated with potential polyposis syndromes (SMAD4, BMPR1A) and KCNJ2, associated with arrhythmia phenotypes, were included in the list of genes considered actionable among pediatric populations." (PMID 29301385, 2018). "Clinically, mutations in the KCNJ2 gene encoding for Kir2.1 induce diseases associated with severe cardiac arrhythmias and increased risk of sudden cardiac death." (PMID 27560040, 2017). "Genetic variations in the genes encoding other cardiac ion channels may contribute significantly into the phenotype of patients with mutations in the KCNJ2 genes, and may facilitate clinical appearance of arrhythmias." (PMID 35456365, 2022). "It was shown that even common genetic polymorphism in the KCNH2 gene may contribute significantly to the clinical appearance of cardiac arrhythmia in patients with KCNJ2 mutations, and may serve as a predictor of symptomatic arrhythmias." (PMID 35456365, 2022). "The loss-of-function mutation of potassium voltage-gated channel subfamily J member 2 (KCNJ2), the encoding gene of Kir2.1, could lead to Andersen–Tawil syndrome accompanied by periodic paralysis, cardiac arrhythmia, and dysmorphic features." (PMID 36531961, 2022). "Andersen–Tawil syndrome (ATS) is caused by mutations in the KCNJ2 gene, which encodes Kir2.1, in patients exhibiting cardiac arrhythmia, periodic paralysis, dental defects, cleft lip/palate, micrognathia, hypertelorism, low-set ears, and limb patterning defects." (PMID 34638799, 2021). "This work adds to the growing set of arrhythmia genes previously assayed by multiplexed assays for either the full protein (KCNJ2, calmodulin) or a portion of the protein (SCN5A, KCNH2)." (PMID 38816749, 2024). "The prevalence of LVNC is generally increased in BAV cohorts, and mutation of KCNJ2, another potassium channel subunit, causes a syndromic presentation of BAV with extracardiac features in addition to arrhythmias." (PMID 38370698, 2024). "SQT3 is a genetic disorder caused by KCNJ2 gene mutation that can cause structural and functional defects in the heart, leading to arrhythmia and sudden cardiac death." (PMID 32328155, 2020). "The expression of miR‐16 increased in the marginal zone of myocardial infarction, inhibited the expression of Kir2.1 (KCNJ2) ion channel and promoted the occurrence of arrhythmia." (PMID 32468736, 2020). "This study aimed to investigate arrhythmia substrates arising from purely cellular electrophysiological differences in SQT3 KCNJ2 mutations, and as such did not consider effects of electrical or intracellular gap junction remodelling or fibrosis." (PMID 28609477, 2017). "The electrophysiological changes of IK1 properties caused by the K346T mutation are very similar to those of the other KCNJ2 mutation found in SQT3S (i.e. D172N; 8) and atrial fibrillation, indicating that K346T likely contributes to arrhythmia generation by affecting the excitability of myocytes." (PMID 24794859, 2014).
Arrhythmia (continued). "A more useful arrhythmia phenotype-LQT and spontaneous VT—was observed in the KCNJ2-T75R cardiacspecific overexpression mouse model." (PMID 37775650, 2023). "MiR-1 is the most abundant microRNA in the adult mouse heart, accounting for 35–40% of the total amount of miRNA MiR-1 directly targets connexin-43, KcnJ2, Kcne1, Ncx1, PP2A/RyR2, and Hcn4 in the adult heart, contributing to the arrhythmias that we and others observed in miR-1 TG adult hearts." (PMID 30936836, 2019). "Up-regulation of miR-1 in MI mice might be involved in the development of life-threatening arrhythmias such as ventricular tachycardia (VT), ventricular fibrillation, and atrioventricular block (AVB) by targeting the mRNAs of ion channel genes, i.e., KCNJ2 and GJA1, respectively." (PMID 29212255, 2017).
short QT syndrome (27 papers, 2012 to 2025). A genetic disease of the electrical system of the heart that consists of a constellation of signs and symptoms, consisting of a short QT interval on an EKG (< 300 ms) that does not significantly change with heart rate, tall and peaked T waves, and a structurally normal heart. "Short QT syndrome type 3 (SQTS3) is a rare arrhythmogenic disease caused by gain-of-function mutations in KCNJ2, the gene coding the inward rectifier potassium channel Kir2.1." (PMID 38261726, 2024). "KCNJ2 variants are also associated in rare familial forms of atrial fibrillation type 9, short QT syndrome type 3 and Catecholaminergic Polymorphic Ventricular Tachycardia (CPVT)." (PMID 34899860, 2021). "Gain-of-function mutations in the KCNJ2 gene encoding Kir2.1 are associated with ventricular arrhythmia like short QT syndrome type 3 or atrial arrhythmia such as congenital atrial fibrillation (AF)." (PMID 32796537, 2020). "Here, we report the identification in an Italian affected family of a novel missense mutation (p.Phe58Ser) in the KCNJ2 gene detected in heterozygosity in a proband affected by autism and borderline for short QT syndrome type 3." (PMID 29615871, 2018). "To date, four missense mutations have been identified in KCNJ2-linked short QT syndrome (SQT3): D172N, M301K, E299V, and K346T, with reports of AF in some patients." (PMID 28609477, 2017). "Gain-of-function KCNJ2 mutations are also potentially life-threatening, underlying variant 3 of the short QT syndrome (SQT3), as well as familial atrial fibrillation (AF)." (PMID 28609477, 2017). "Gain-of-function mutations in KCNJ2-encoded Kir2.1 channels underlie variant 3 (SQT3) of the short QT syndrome, which is associated with atrial fibrillation (AF)." (PMID 28609477, 2017). "A gain-of-function KCNJ2 D172N mutation in KCNJ2-encoded Kir2.1 channels underlies one form of short QT syndrome (SQT3), which is associated with increased susceptibility to arrhythmias and sudden death." (PMID 29290967, 2017). "So far, gain-of-function mutations in KCNQ1, KCNH2, and KCNJ2 have been associated only with rare cases of short QT syndrome (SQTS) and/or AF." (PMID 24972929, 2014). "The KCNJ2 gene mutations induce short QT syndrome (SQT3) by directly increasing the IK1 current." (PMID 32328155, 2020). "However, the KCNJ2 E299V mutation is distinguished from other representative gene mutations that can induce the short QT syndrome (SQT3) in that it increased IK1 current by impairing the inward rectification of K+ channels." (PMID 32328155, 2020). "Short QT syndrome is a relatively recently-described cardiac channelopathy associated with a high risk of ventricular arrhythmia and sudden death, and mutations in KCNJ2 have recently been reported in patients with short QT syndrome and an autism–epilepsy phenotype." (PMID 26297560, 2015). "Regarding the Short QT Syndrome, there is only one variation with contradictory interpretations (KCNJ2:c.431G>A)." (PMID 37946154, 2023). "KCNJ2 gain-of-function mutations V93I and D172N associate with increased IK1, short QT syndrome type 3 and congenital atrial fibrillation." (PMID 28711067, 2017). "Gain-of-function mutations in the KCNJ2 gene, that encodes KIR2.1 protein underlying IK1, associate with ventricular (short QT syndrome type 3 (SQT3)) and atrial (congenital atrial fibrillation (AF)) phenotypes." (PMID 28711067, 2017). "The loss-of-function (LoF) mutations of the KCNJ2 gene are known to be causative for LQTS with variable skeletal and muscular phenotype and catecholaminergic polymorphic ventricular tachycardia, and gain-of-function (GoF) mutations can cause atrial fibrillation and Short QT syndrome." (PMID 35456365, 2022).
periodic paralysis (26 papers, 2004 to 2025). "Andersen‐Tawil syndrome involves periodic paralysis with characteristic facial and skeletal anomalies and cardiac manifestations due to mutations in the KCNJ2 gene." (PMID 41018978, 2025). "The mutant KCNJ2 variant in our patient also accounts for her muscle weakness and periodic paralysis, as potassium imbalance is known to exacerbate arrhythmias and muscle symptoms." (PMID 41255772, 2025). "Long QT syndrome type 7 (Andersen–Tawil syndrome, ATS), which is caused by KCNJ2 gene mutation, often leads to ventricular arrhythmia, periodic paralysis and skeletal malformations." (PMID 38528561, 2024). "In Andersen–Tawil syndrome, a rare disorder of periodic paralysis caused by mutations in the KCNJ2 gene, which encodes the inward rectifier potassium channel Kir 2.1, stress or corticosteroids exacerbate the symptoms." (PMID 24281399, 2014). "Kir2.1 channelopathy stemming from KCNJ2 mutation manifests as Andersen–Tawill syndrome, where this channel is nonfunctional, and in addition to distinctive craniofacial features, patients suffer from periodic paralysis and long QT syndrome (LQT)." (PMID 41465576, 2025). "However, the expression of Kir2.1 channels is not limited to the heart and loss-of-function mutations in KCNJ2 may also lead to periodic paralysis, dysmorphic features and neurocognitive problems." (PMID 25691870, 2015). "Dominant mutations in KCNJ2 have been suggested to associate with Andersen‐Tawil syndrome (MIM170390), a channelopathy characterized by periodic paralysis, ventricular arrhythmias, and dysmorphic facial or skeletal features." (PMID 32583964, 2020). "We obtained a Japanese nationwide case series of 119 index patients (108 men and 11 women) clinically suspected of periodic paralysis, and a gene panel analysis, targeting CACNA1S, SCN4A, and KCNJ2 genes, was conducted." (PMID 36779057, 2023).
atrial fibrillation (20 papers, 2006 to 2025). A disorder characterized by an electrocardiographic finding of a supraventricular arrhythmia characterized by the replacement of consistent P waves by rapid oscillations or fibrillatory waves that vary in size, shape and timing and are accompanied by an irregular ventricular response. "The KCNJ2 gene that encoded Kir2.1 and Kir2.2 proteins of inward rectifier potassium channels was associated with the pathogenesis of atrial fibrillation." (PMID 35387267, 2022). "“Loss-of-function” or “Gain-of-function” mutations of KCNJ2 gave rise to atrial fibrillation." (PMID 35387267, 2022). "Atria-Enriched GJA5, KCNA5 and NPPA, RA-Enriched HCM4, MIR100HG, REC114 and SMAD7 and Ventricles-Enriched KCNJ2, MYH7, PHLDB2, RPL2L and SLC35F1 were associated with atrial fibrillation." (PMID 34088950, 2021). "Mutations in KCNJ2 and KCNE1-5 rarely cause typical atrial fibrillation in a referral clinic population." (PMID 16887036, 2006). "Mutations in potassium channels, KCNJ2 and KCNE1-5, rarely cause typical atrial fibrillation in a referral clinic population." (PMID 16887036, 2006). "We sought to determine if mutations in KCNJ2 and KCNE1-5 are a common cause of atrial fibrillation." (PMID 16887036, 2006). "MiR-26 can also suppress atrial fibrillation (AF) and cardiomyocyte hypertrophy by targeting β-MHC, GSK3β, GATA4, KCNJ2, and PLCβ1." (PMID 38195542, 2024).
Ventricular arrhythmia (17 papers, 2006 to 2026). "We dissected the prototypic KCNJ2 locus, encoding a potassium channel associated with ventricular arrhythmia susceptibility." (PMID 41526351, 2026). "Clinical and genotype characteristics of KCNJ2 mutation-carrying patients with ventricular arrhythmia diagnosed as CPVT in the literature." (PMID 34899860, 2021). "However, overexpression of miR-1 in adult rats increases the risk of ventricular arrhythmias by downregulating Kir2.1 (encoded by KCNJ2) and Cx43 leading to reduced conduction and cardiomyocyte depolarization." (PMID 33712058, 2021). "Citing its relationship to other disorders of myocellular repolarization, predisposition to ventricular arrhythmias, and the purported presence of a prolonged QT interval in 71% of all KCNJ2 mutation carriers, it had been suggested that ATS be classified as LQT7." (PMID 16943893, 2006). "Patients with ATS and KCNJ2 mutations demonstrate a distinct change in U wave morphology, an electrocardiographic characteristic associated with frequent premature ventricular beats and nonsustained VT, potentially demonstrating an increased vulnerability to ventricular arrhythmia." (PMID 16943893, 2006).
long QT syndrome (15 papers, 2012 to 2025). "A subtype of long QT syndrome (long QT 7), Andersen–Tawil syndrome is a rare genetic disease predominantly caused by pathogenic variants in the KCNJ2 gene, which encodes for Kir2.1." (PMID 37446026, 2023). "For instance, patient 2 was a carrier of a pathogenic variant (c.566G > T, p.Arg189Ile; rs199473381) in the KCNJ2 gene, which has been associated with congenital long QT syndrome." (PMID 32695137, 2020). "KCNJ2 is a biologically plausible locus influencing QT, as it harbors mutations causing rare, familial forms of long QT syndrome." (PMID 22912591, 2012). "They included the Drosophila ortholog of the human potassium channel gene KCNJ2 (Irk1)—the KCNJ2 mutation has been associated with long QT syndrome in human hearts —as well as a voltage-gated channel gene (KCNQ) that has been known to function in cardiac muscle contraction." (PMID 38139143, 2023). "Limberg and collaborators have identified two novel heterozygous KCNJ2 mutations (p.N318S, p.W322C) located in the C-terminus of the Kir2.1 potassium channel subunit in a large set of patients with congenital long-QT syndrome." (PMID 24065925, 2013). "No other pathogenic mutations were detected in sarcomere-, ion channel-, cardiomyopathy- or other long QT syndrome-related genes, and the proband’s father (III-4) and uncle (III-2) carried no mutations in the KCNJ2 gene." (PMID 38528561, 2024).
channelopathies (9 papers, 2014 to 2025). "About 60%–70% of patients with ATS exhibiting channelopathies have the KCNJ2 variant, which encodes the α subunit of the K+ channel protein, Kir2.1, resulting in complete loss of function in relative K+ channel functions." (PMID 41255772, 2025). "Hypokalemic periodic paralysis is a genetically heterogeneous channelopathy that has been linked to mutations in genes encoding three ion channels CACNIAS, SCN4A, and KCNJ2 predominantly." (PMID 25893123, 2015).
epilepsy (9 papers, 2013 to 2024). A brain disorder characterized by episodes of abnormally increased neuronal discharge resulting in transient episodes of sensory or motor neurological dysfunction, or psychic dysfunction. "Although it is formally possible that the KCNJ2 mutation in cis with KCNJ10 contributes separately to SQT3S or autism–epilepsy pathogenesis, each playing a clear distinctive role, this conclusion appears to be too simplistic." (PMID 24794859, 2014). "In consideration of species conservation, we jointly analyzed the sequencing results of human peripheral blood samples and mouse tissue samples, and four genes (GADD45B, TMCC3, TPGS2, and KCNJ2) were identified as hub genes in IS and epilepsy." (PMID 37792772, 2023). "Recently, some authors detected a novel mutation (p.Lys346Thr) in the KCNJ2 in monozygotic twins displaying SQT3s and autism-epilepsy phenotype, suggesting the existence of a Kir2.1 role in neuropsychiatric disorders and epilepsy." (PMID 27064559, 2016).
myocardial infarction (8 papers, 2015 to 2024). Gross necrosis of the myocardium, as a result of interruption of the blood supply to the area, as in coronary thrombosis. "Researchers have shown that the injection of miR-1 into the ischemic myocardium of rats with myocardial infarction (MI) led to decreases in GJA1 and KCNJ2, which are the target genes of miR-1." (PMID 34646152, 2021).
small cell lung carcinoma (8 papers, 2015 to 2025). Small cell lung cancer (SCLC) is a highly aggressive malignant neoplasm, accounting for 10-15% of lung cancer cases, characterized byrapid growth, and early metastasis. "KCNJ2 is upregulated in small-cell lung cancer cells, and enhance multidrug resistance by activating the RAS/MAPK pathway." (PMID 36864422, 2023). "Moreover, KCNJ2, another Kir channel family, was found upregulated in small-cell lung cancer with a significant role in clinical stages and treatment response." (PMID 36768373, 2023). "For example, KCNJ2 regulates the expression of MRP1/ABCC1 to regulate cell growth and chemoresistance in small-cell lung cancer." (PMID 36100894, 2022).
Hypertension (7 papers, 2017 to 2026). The presence of chronic increased pressure in the systemic arterial system. "Six genes (PTGS2, TBXA2R, ZNF101, KCNJ2, MSRA, and CMTM5) have been reported to be associated with hypertension." (PMID 39854379, 2025).
Cooks syndrome (6 papers, 2021 to 2025). Cooks syndrome is a malformation syndrome affecting the apical structures of digits and presenting with hypo/aplasia of nails and distal phalanges. "Misexpression of KCNJ2 is the cause of Cooks syndrome (MIM 106995), a congenital limb malformation characterized by aplasia of nails and short digits." (PMID 39257002, 2024). "However, a new TAD (neo-TAD) appears to contain regulatory elements of the SOX9 gene and a copy of the KCNJ2 gene, which results in abnormal KCNJ2 expression and malformations associated with Cooks syndrome." (PMID 39872109, 2023). "A related study showed that genomic duplication of a murine boundary between Kcnj2 and Sox9 TADs resulted in the formation of new TADs, the ectopic activation of Kcnj2 and the onset of Cooks Syndrome—another limb malformation." (PMID 34385432, 2021). "At the Sox9 locus, duplications encompassing the neighbor Kcnj2 gene lead to the formation of a “neo-TAD” in which Kcnj2 is miss-regulated by interactions with new enhancers, leading to a limb malformation phenotype known as Cooks syndrome." (PMID 34295901, 2021). "By modelling Cooks syndrome, a congenital limb malformation, genomic duplications upstream of SOX9/Sox9 creates a new TAD (neo-TAD) containing both the Kcnj2 gene and the Sox9 regulatory region leading to limb malformation due to ectopic Kcnj2 expression." (PMID 36114905, 2022).
cardiomyopathy (5 papers, 2015 to 2024). A disease of the heart muscle or myocardium proper. "LQT7 is a rare cardiomyopathy with abnormal electrophysiology, and 70% of cases are related to the Kir2.1 inward rectifier potassium channel protein, which is encoded by the KCNJ2 gene, in ventricular muscle, skeletal muscle and brain tissue." (PMID 38528561, 2024).
catecholaminergic polymorphic ventricular tachycardia (5 papers, 2017 to 2022). "In addition, several studies have also reported that KCNJ2 mutations are associated with catecholaminergic polymorphic ventricular tachycardia." (PMID 34483927, 2021).
mood disorder (5 papers, 2013 to 2023). A cognitive disorder a disturbance in which the person's mood is hypothesized to be the main underlying feature. "Seizures and mood disorders are associated with mutations in KCNJ2 that encode the inwardly rectifying K+ channel (Kir2.1)." (PMID 37763219, 2023). "Individuals harboring mutations in KCNJ2 may also present mood disorders and seizures." (PMID 24794859, 2014).